ACSL4 (acyl-CoA synthetase long chain family member 4)
Diseases named in the same sentence as ACSL4 in open-access papers (continued):
Sharing a sentence is not in itself a finding about the gene and the disease.
glioblastoma (10 papers, 2018 to 2025). The most malignant astrocytic tumor (WHO grade IV). "For example, miR-670-3p was found to suppress ferroptosis of human glioblastoma by inhibiting ACSL4, suggesting that inhibition of miR-670-3p can be an adjuvant strategy to treat glioblastoma." (PMID 36507355, 2022). "In this regard, genetic or pharmacological inhibition of ACSL4 suppresses ferroptosis in glioblastoma." (PMID 36591531, 2022). "This suggests that ACSL4 is required for miR-670-3p to regulate ferroptosis and cell growth in glioblastoma." (PMID 36408273, 2022). "The chemical inhibition, stable silencing, or depletion of ACSL4 demonstrated it can diminish necrosis and aggressiveness of glioblastoma." (PMID 36507355, 2022). "Independent experimental evidence showed that suppressing miR-670-3p, which targets ACSL4, also modulates the sensitivity of glioblastoma cells to ferroptosis-mediated cell death." (PMID 36591531, 2022). "MiR-670-3p inhibitor was able to target ACSL4 to inhibit the growth of glioblastoma and promote ferroptosis of glioblastoma." (PMID 36408273, 2022). "Specifically, the study aimed to evaluate whether boric acid treatment in U87 glioblastoma cells could serve as a potential therapeutic strategy for glioblastoma by targeting the SOX10/GPx4/ACSL4 signalling axis." (PMID 40159622, 2025). "Overexpression of RAS-selective lethal 3 (RSL3) induces ferroptosis through the nuclear factor kappa-B (NF-κB) pathway in glioblastoma, whereas microRNA-670-3p inhibits Acyl-CoA Synthetase Long-Chain Family Member 4 (ACSL4) expression, suppressing glioblastoma cell ferroptosis." (PMID 39857625, 2024). "A study regarding glioblastoma also showed that a knockdown of HSPB1 evidently induced ferroptosis and enhanced ACSL4 stability via reducing SUMOylation of ACSL4." (PMID 37509438, 2023). "Through the determination of ferroptosis-related protein expression, we found that the significant decrease of GPX4, accompanied by the constant expression of xCT and ACSL4, suggesting GPX4 was a pivotal target for DHA-activated ferroptosis in glioblastoma." (PMID 32452511, 2020). "In glioblastoma (GBM), HIF-2α induced by the prolyl hydroxylase (PHD) inhibitor roxadustat, upregulated ferroptosis regulatory genes such as ACSL4, PTGS2, and CHAC1, to enhance lipid peroxidation and erastin-induced ferroptosis, leading to the suppression of GBM cell growth in vitro and in vivo." (PMID 37048123, 2023).
Hepatic steatosis (10 papers, 2012 to 2024). Steatosis is a term used to denote lipid accumulation within hepatocytes. "On the other hand, miR-133b also directly targets enzymes involved in fatty acid biosynthesis, such as Acaca or Acsl4, whose inhibition may play a role in the decreased hepatic steatosis in EV mice." (PMID 36499248, 2022). "Currently, it is not clear how deficiency in ACSL4 potentially contributes to hepatic steatosis in HFD mice or the pathogenesis of human NAFLD." (PMID 24879802, 2014). "Additionally, peripheral blood leukocyte ACSL4, CRLS1, CTP1A, SIGIRR, SSBP1, and ZNF622 genes containing DMPs might be used as serum biomarkers to stratify NAFLD patients into groups with simple hepatic steatosis and NASH." (PMID 35433752, 2022).
Parkinson disease (10 papers, 2021 to 2025). A progressive degenerative disorder of the central nervous system characterized by loss of dopamine producing neurons in the substantia nigra and the presence of Lewy bodies in the substantia nigra and locus coeruleus. "The inhibition of ACSL4 can reduce the damage caused by Parkinson's disease by reducing lipid and reactive oxygen species levels." (PMID 38839927, 2024). "By preventing ACSL4 activity, triacsin C can alleviate parkinson’s disease (PD); and clausenamide can also alleviate behavioural impairments in PD animal models by preventing the nuclear translocation of ALOX5." (PMID 40951640, 2025). "Neuronal lineage exosomes are less studied, but NSC-Exos carrying CDC42 reduce ACSL4-driven ferroptosis in Parkinson’s models." (PMID 41190075, 2025). "The present study also confirms at the genetic level that ACSL4 may promote the progression of key pathological stages of Parkinson’s disease through ferroptosis." (PMID 38127902, 2023). "Green module was obtained for five Parkinson’s disease FRGs (MAP3K11, SNX4, SIRT2, NUPR1, and ACSL4)." (PMID 38127902, 2023). "ACSL4 would play a role in lipopolysaccharide (LPS)-induced microglia inflammation and has implications for diseases such as Parkinson’s disease and AD; however, the mechanism is not clear." (PMID 37520121, 2023). "Given that ACSL4 and GPX4 are pivotal regulators of ferroptosis, lncRNA NEAT1 might modulate ferroptosis via these molecules, presenting a promising therapeutic approach for Parkinson’s disease." (PMID 39280701, 2024).
renal cell carcinoma (10 papers, 2021 to 2025). "However, the regulatory mechanisms governing ACSL4 expression in renal cell carcinoma (RCC) remain unclear." (PMID 40756764, 2025). "In renal cell carcinoma cells, receptor protein AIM2 promotes FOXO3a phosphorylation and proteasome degradation, thereby abating its transcriptional effect on ACSL4 and inhibiting ferroptosis." (PMID 40050614, 2025).
cholangiocarcinoma (9 papers, 2020 to 2025). A carcinoma that arises from the intrahepatic biliary tree (intrahepatic cholangiocarcinoma) or from the junction, or adjacent to the junction, of the right and left hepatic ducts (hilar cholangiocarcinoma). "Furthermore, ACSL4 isoforms could be used to divided HCC, cholangiocarcinoma (CCA) and hepatic metastases." (PMID 35910359, 2022).
myocardial ischemia (9 papers, 2022 to 2026). A disorder of cardiac function caused by insufficient blood flow to the muscle tissue of the heart. "In addition, protein ACSL4 in the arachidonic acid metabolism pathway was down-regulation by baicalin to inhibit ferroptosis and then prevent myocardial ischemia/reperfusion (I/R) injury." (PMID 35888777, 2022). "During myocardial ischemia/reperfusion injury (MI/RI), ATF3 promotes ferroptosis by upregulating the expression of ACSL4, leading to aggravated cardiomyocyte damage." (PMID 41550926, 2025).
viral infections (9 papers, 2022 to 2025). "ACSL1 and ACSL4 inhibitions prevent ferroptosis during viral infections, thereby protecting the host." (PMID 38075884, 2023). "Viral infection can induce ferroptosis by lipid ROS synthesis in various mechanisms, such through the function of ACSL4." (PMID 38075884, 2023). "Our results suggest that ACSL4 has multiple roles in viral infection and is a potential target for antiviral therapy." (PMID 35038927, 2022). "Additionally, the study observed that viral infection increases the expression levels of ACSL4, FTH1, and SLC7A11, but they gradually decrease as the viral infection progresses." (PMID 40661982, 2025). "This suggests that viral infection may upregulate ACSL4, activating ferroptosis, but it also upregulates the expression of SLC7A11 and FTH1 to inhibit the ferroptosis process." (PMID 40661982, 2025). "Nevertheless, whether AA would induce ferroptosis through the ACSL4-LPCAT3-POR pathway in the context of neuroinvasive virus infection is unclear." (PMID 38490434, 2024). "It is also suggested that ACSL4 could be a target for combating viral infections, and the use of ACSL4 inhibitors, such as rosiglitazone and pioglitazone, can decrease the viral load of coronaviruses." (PMID 36978981, 2023). "Most importantly, ferroptosis inhibitors, including two FDA-approved drugs, rosiglitazone (ROSI; ACSL4 inhibitor) and pioglitazone (PIO; ACSL4 inhibitor), decreased the viral load of human enteroviruses and coronaviruses, suggesting that ACSL4 is a target for counteracting viral infection." (PMID 35038927, 2022). "The mRNA expression level of ACSL4 increased slightly during CV-A6 infection, especially at 36 h postinfection, while no significant changes were observed in the protein expression levels of ACSL4 during viral infection." (PMID 35038927, 2022). "However, the influence of ACSL4 on ferroptosis during viral infections has yet to be defined." (PMID 35038927, 2022). "Simultaneously, viral infection activated the COX2 and ACSL4 pathways, which promoted the release of inflammatory mediators and suggested the onset of ferroptosis." (PMID 40872344, 2025). "In viral infection, ACSL4 exhibited the similar promoting effect for SARS-CoV-2, IAV, and Zika virus (ZIKV), demonstrating a unifying mechanism of lipid peroxidation in virus infections." (PMID 38075884, 2023). "However, in the virus-infected mock cells, the mRNA levels of NCOA4, ACSL4, and STEAP3 considerably increased while being down-regulated in the DDX3X-silenced cells with virus infection." (PMID 39155369, 2024). "As the viral infection progresses, the cell initiates a negative feedback mechanism to resist the virus’s control over the ferroptosis process, resulting in decreased expression of ACSL4 and SLC7A11." (PMID 40661982, 2025). "Therefore, this ACSL4-dependent LPO, with its relevant pathways in ferroptosis, e.g., iron metabolism, provides a distinct perspective to understand the mechanism of immune evasion in cancers, as well as in viral infections." (PMID 39343834, 2024). "Moreover, shrunken mitochondria, a morphological hallmark of ferroptosis, were observed in ACSL4+/+ cells upon CV-A6 infection (red arrow) but not in mock-infected cells or in ACSL4−/− cells with virus infection." (PMID 35038927, 2022).
liver disease (8 papers, 2018 to 2026). "Furthermore, ClinASO generated a potent ASO targeting ACSL4 genes implicated in metabolic dysfunction-associated liver disease (MASLD)." (PMID 42112101, 2026). "While previous studies have focused on the link between BA metabolism and liver diseases, the specific interaction and regulatory mechanisms between ACSL4 and BAs remain largely unknown." (PMID 39268355, 2024). "Previous studies suggested a role for ACSL4 in a non-apoptotic cell death mechanism, ferroptosis, in several liver diseases including viral hepatitis." (PMID 36829466, 2023). "Interestingly, our transcriptome array indicated that HVI-1 co-infection up-regulated only ACSL4, but not other isoforms, in a liver-disease stage specific manner." (PMID 30138348, 2018).
liver fibrosis (8 papers, 2022 to 2026). "ACSL4 is also implicated in pathological processes such as the inflammatory response and liver fibrosis in the liver." (PMID 37372148, 2023). "suggesting that ACSL4 inhibits the onset and progression of hepatic fibrosis through the iron death pathway." (PMID 40148434, 2025). "In the liver fibrosis model, upregulating the expression of miR-3667-3p significantly reduced ACSL4 levels, alleviated the degree of liver fibrosis, and improved liver function." (PMID 40148434, 2025). "ACSL4 was lowly expressed in the liver fibrosis model and we overexpressed ACSL4, ROS, Iron, MDA with elevated expression and GPX4, GSH with reduced expression." (PMID 40148434, 2025). "Previous studies have demonstrated the efficacy of abemaciclib in attenuating liver injury and liver fibrosis in a mouse model of nonalcoholic fatty liver disease by selectively inhibiting ACSL4 expression." (PMID 37893066, 2023). "Additionally, it aimed to conduct a preliminary analysis of the molecular mechanism targeting miR-3667-3p/ACSL4 (Long-chain acyl-CoA synthetase 4), thereby providing novel molecular targets for liver fibrosis." (PMID 40148434, 2025). "In contrast, the metabolic NASH-HCC model does not exhibit any signs of liver fibrosis and is hence largely unaffected by Acsl4 deficiency." (PMID 35963845, 2022). "Specifically, CBD appears to exert its anti-liver fibrosis and antioxidative effects by activating CB2R, inhibiting the expression of α-SMA and ACSL4 proteins, and enhancing the expression of SLC7A11 protein, thereby alleviating liver damage." (PMID 40160456, 2025). "These extracts administered to mice also inhibited ferroptosis in the liver by regulating the expression of Acyl-CoA synthetase long chain family member 4 (ACSL4), solute carrier family 7 member 11 (SLC7A11) and glutathione peroxidase 4 (GPX4), thus reducing the occurrence of liver fibrosis." (PMID 37032323, 2023).
lung adenocarcinoma (8 papers, 2016 to 2025). A carcinoma that arises from the lung and is characterized by the presence of malignant glandular epithelial cells. "In an analysis of the TCGA database and validation samples, ACSL4 was frequently downregulated in lung adenocarcinoma, and a lower ACSL4 expression was associated with a poorer prognosis." (PMID 36497375, 2022). "Given the association between the ACSL4 expression level and patient prognosis, we next investigated the function of ACSL4 in lung adenocarcinoma." (PMID 34053456, 2021). "ACSL4 functions as an anti-tumor agent in lung adenocarcinomas by suppressing tumor survival and invasiveness, and promoting ferroptosis." (PMID 36497375, 2022). "We first knocked down (shACSL4) or overexpressed ACSL4 (oeACSL4) in 4 lung adenocarcinoma cell lines, including A549, H322, H1299, and H460." (PMID 34053456, 2021). "ACSL4 plays a tumor-suppressive role in lung adenocarcinoma by suppressing tumor survival/invasiveness and promoting ferroptosis." (PMID 34053456, 2021). "In summary, this is the first study demonstrating ACSL4 acts as a tumor suppressor in lung adenocarcinoma." (PMID 34053456, 2021). "ACSL4 was frequently downregulated in lung adenocarcinoma when analyzing both the TCGA database and the validation samples, and the lower ACSL4 expression was correlated with a worse prognosis." (PMID 34053456, 2021). "As ACSL4 was rarely studied in lung adenocarcinoma, we then tried to validate the ACSL4 expression level in lung adenocarcinoma patient samples obtained from our hospital." (PMID 34053456, 2021). "In this study, we used the gene expression data from the TCGA database to characterize the patient prognosis stratified based on ACSL4 expression and understand the ACSL4-related pathways in lung adenocarcinoma." (PMID 34053456, 2021). "In the current study, we performed a serial of experiments to assess the function of ACSL4 in lung adenocarcinoma cells." (PMID 34053456, 2021). "Similar to ACSL4 overexpression, erastin treatment impaired cell migration, invasion, and survival in lung adenocarcinoma cells; in contrast, ferroptosis inhibitor Ferrostatin 1 demonstrated the opposite effects, like those in ACSL4 knockdown cells." (PMID 34053456, 2021). "After culturing cells in high palmitic acid-containing media for 48 h, ACSL4 expression was decreased in all 4 lung adenocarcinoma cell lines." (PMID 34053456, 2021). "Our data confirmed that ACSL4 expression positively regulated response to oxidative stress pathway in lung adenocarcinoma and negatively correlated with GPX4 in ferroptotic cell death signaling pathways." (PMID 34053456, 2021). "Our study provided new evidence that the high-fat diet suppresses ferroptosis via down-regulating ACSL4 in lung adenocarcinoma." (PMID 34053456, 2021). "Previous studies showed ACSL4 displayed both tumor-promoting and tumor-suppressive functions in different tumor types, and the role of ACSL4 in lung adenocarcinoma was still elusive." (PMID 34053456, 2021). "Future studies are needed to completely understand the functional difference of ACSL4 between lung adenocarcinoma and other cancer types." (PMID 34053456, 2021). "Overall, these results suggest that ACSL4 exhibits tumor suppressor roles in lung adenocarcinoma, and it could inhibit the growth and migration of the tumor cells and promote ferroptosis." (PMID 34053456, 2021). "ACSL4 was also a promising prognostic factor in lung adenocarcinoma." (PMID 34053456, 2021). "As ACSL4 could exhibit either tumor-suppressive or tumor-promoting functions, it is worth specifying the role of ACSL4 based on the specific cancer type, including lung adenocarcinoma where ACSL4 is rarely studied." (PMID 34053456, 2021). "However, the function and clinical significance of ACSL4 in lung adenocarcinoma remain elusive." (PMID 34053456, 2021).
lung adenocarcinoma (continued). "Moreover, both the transwell assay and wound healing assay indicate that knockdown of ACSL4 could enhance cell invasion and migration for all 4 lung adenocarcinoma cell lines, suggesting that ACSL4 acts as a tumor suppressor in lung adenocarcinoma." (PMID 34053456, 2021). "Furthermore, using both the cell line model and mouse xenograft model, we found that high-fat treatment could downregulate ACSL4 expression in lung adenocarcinoma cells, thus enhancing cell survival and migration and reducing ferroptotic cell death." (PMID 34053456, 2021). "Moreover, considering the anti-tumor effect of ACSL4, it may be a new therapeutic target for the targeted therapy of lung adenocarcinoma." (PMID 34053456, 2021). "LPCAT3/ACSL4 knockout can protect lung adenocarcinoma cells from ferroptosis, while ectopic expression of LPCAT3 and ACSL4 has the opposite effect." (PMID 40724837, 2025). "As clinical and gene expression data indicated that high ACSL4 expression correlates with improved prognosis and enhanced ferroptosis in lung adenocarcinoma patients, we next investigated whether altering ACSL4 expression level could affect tumor growth and invasiveness in lung adenocarcinoma." (PMID 34053456, 2021). "Therefore, both in vitro and in vivo results indicate that ferroptosis-inducing agents could inhibit the progression of lung adenocarcinoma and the high-fat diet could partially attenuate this anti-tumor effect by downregulating the tumor suppressor gene ACSL4." (PMID 34053456, 2021).
type 2 diabetes mellitus (8 papers, 2017 to 2025). A type of diabetes mellitus that is characterized by insulin resistance or desensitization and increased blood glucose levels. "Nobiletin may exert therapeutic effects in type 2 diabetes by downregulating ACSL4, with the study confirming that administration of the drug at a dose of 5 mg/kg yielded a beneficial effect in the rat model." (PMID 41288931, 2025). "Furthermore, canagliflozin (Cana), a clinical-approved drug for type 2 diabetes, mimics glucose starvation and inhibits the growth of ACSL4-low xenograft tumors." (PMID 39563427, 2024). "For instance, quercetin mitigates MIRI by inhibiting oxidative stress, preventing apoptosis and reducing calcium overload; nobiletin could alleviate MIRI in type 2 diabetic rats through the inhibition of ferroptosis; and baicalin prevents against MIRI by suppressing ACSL4‐controlled ferroptosis." (PMID 40722225, 2025).
Alzheimer disease (7 papers, 2022 to 2025). A progressive, neurodegenerative disease characterized by loss of function and death of nerve cells in several areas of the brain leading to loss of cognitive function such as memory and language. "For example, in Alzheimer’s disease (AD) models, astrocytes take up oxidized lipids released by stressed neurons and esterify them into LDs via acyl-CoA synthetase (ACSL4), thereby protecting neurons from lipid-induced damage." (PMID 41404624, 2025). "Researchers found that ALDH2 inhibits Alzheimer's disease-induced myocardial injury by regulating lipid peroxidation and ACSL4-dependent ferroptosis." (PMID 36820405, 2023). "However, a recent study demonstrated for the first time that Alda-1 could rescue cardiac contractile dysfunction induced by Alzheimer's disease through the inhibition of ACSL4-dependent ferroptosis." (PMID 35646953, 2022).